TNF (tumor necrosis factor)
Diseases named in the same sentence as TNF in open-access papers (continued):
Sharing a sentence is not in itself a finding about the gene and the disease.
colitis (continued). "It improves acetic acid-induced colitis by reducing oxidative stress by decreasing nitric oxide (NO) production, increasing superoxide dismutase (SOD) expression, and inhibiting the production of TNF-α and IFN-γ in rats." (PMID 34068714, 2021). "In the present study, it was found that serum levels of tumor necrosis factor-α (75 vs. 44 pg./ml), interleukin-6 (41 vs. 21 pg/ml), and nitric oxide (24 vs. 6 μm/ml) in TNBS-induced untreated colitis treatment were significantly increased as compared to healthy control." (PMID 34912469, 2021). "Purification of FAHF-2 using butanol extraction did not affect the ability of B-FAHF-2 to suppress TNF-α production ex vivo from human PBMCs and colonic mucosa nor its ability to abrogate colitis in a murine model." (PMID 34926527, 2021). "Both IL-6 and TNF-α levels in SP-treated mice (P < 0.05) were significantly reduced compared with those in mice in the DSS group, indicating the effective regulation of inflammatory factors by SP in the colonic tissue of mice with colitis." (PMID 34901119, 2021). "For example, caffeic acid, tea polyphenols, salvianolic acid, and sesamol could ameliorate colitis by reducing the levels of IL-1β, IL-6, TNF-α, and other pro-inflammatory cytokines in DSS-induced colitis mice." (PMID 34867926, 2021). "The mRNA expression levels of TNFα, IL-1β, and IL-6 were increased by nearly 12-, 18-, and 16-fold, respectively, and the secretion levels of TNFα, IL-1β, and IL-6 were elevated by approximately 2-, 10-, and 3-fold, respectively, in DSS-induced colitis." (PMID 34880751, 2021). "Also in this study, it was shown that cytokines produced by Th1 (i.e., TNF-α, IFN-γ) and Th17 cells (i.e., IL-17) or promoting Th17 cell differentiation (IL-1β, IL-6) were significantly increased in T cell transfer colitis mice compared to control mice." (PMID 34248633, 2021). "In addition to IL-6 and IL-1β, earlier studies reported TNF-α-induced epithelial barrier dysfunction in rat colon via downregulation of occludin and E-cadherin and in DSS-induced colitis in mice." (PMID 33669494, 2021). "Current findings indicated that the administration of 400 mg/kg Aloe vera extract rectally on experimental colitis in rats can significantly attenuate the increased levels of TNF-a, IL-6, NO, MPO, and MPA and reduce the inflammations as compared to the TNBS-induced colitis model." (PMID 34912469, 2021). "A patient with colitis grade 3, who did not respond to either steroids or anti-TNF-α, was treated with anti-IL6, with event resolution." (PMID 34208218, 2021). "Moreover, TNF-α upregulated the expression of mucin secretion and increased the expression of MUC6, contributing to the defective mucus layer in colitis." (PMID 33807999, 2021). "However, oral gavage of NK210 and/or NK219 suppressed cyclophosphamide-induced colitis: they increased IFN-γ, TNF-α, and IL-10 expression, but decreased myeloperoxidase activity and IFN-γ to IL-10 and TNF-α to IL-10 expression ratios in the colon." (PMID 34667205, 2021). "In a murine DSS-induced colitis model, the administration of polyphenols induced a downregulation of inflammatory markers such as the monocyte chemoattractant protein 1 (MCP1) and tumor necrosis factor α (TNFα)." (PMID 33572926, 2021). "Consistently, blockade of IL‐18 by administration of a monoclonal antibody or anti‐sense IL‐18 mRNA could alleviate DSS‐ and trinitrobenzene sulfonic acid‐induced colitis in mice due to decreased production of IFN‐γ and TNF." (PMID 33491282, 2021). "While the wild type mice survived DSS-induced colitis, MSC-/- mice showed increased production of pro-inflammatory cytokines (e.g., IL-22, IL-6, TNF-α) in the gut, with more infiltrating immune cells in colon tissues, reduced body weight, and earlier onset of death." (PMID 34992594, 2021).
colitis (continued). "The present study confirms that HFD augmented the severity of experimental colitis as documented by the increased DAI index, the colonic tissue weight and upregulated colonic expression of proinflammatory biomarkers TNF-α, IL-1β and IL-6 mRNA compared to the mice fed an SD." (PMID 33557311, 2021). "Oral administration of NK210 and/or NK219 did not affect colitis-related colon shortening, myeloperoxidase activity, and TNF-α and IL-10 expression in the colon." (PMID 34667205, 2021). "In another study, crocin (100 and 200 ppm~1 and 2% w/v) made a significant decrement in the levels of mRNA expression of TNF-α, IL-1β, IL-6, IFN-γ, NF-κB, COX-2, and iNOS and propagated Nrf2 mRNA expression in the colorectal mucosa following dextran sodium sulfate-induced colitis." (PMID 34956439, 2021). "Moreover, the acute colitis produced a strong induction of mRNA expression levels of TNF-α, IL-1β, IL-6 and CXCL10, ranging from 233.5 ± 24.0% for IL6 to 663.5 ± 195.8% for TNF-α, in WTDSS mice compared to control group (p <0.05)." (PMID 34483912, 2021). "Given the important role of TNF-α in IBD progression, Murthy and his co-workers operated a thioketal delivery system, which locally released TNF-α siRNA in response to reactive species at the site of inflammation to treat DSS-induced colitis in mice." (PMID 35052764, 2021). "As TNFα, IL-1β, and IL-6 play crucial roles in the pathogenesis of colitis and cinacalcet suppressed the production of those inflammatory cytokines, we assessed the anti-inflammatory effect of cinacalcet on DSS-induced colitis." (PMID 34880751, 2021). "Moreover, RX821002 reduced the production of inflammatory cytokines in colonic homogenates, such as TNFα and IL-1β, when compared with DSS-induced colitis." (PMID 34884737, 2021). "IAP requires TLR4 signaling to mediate its anti-inflammatory effects, as IAP ameliorated colitis and inhibited IL-6 and TNF-α production in WT but not in TLR4-KO mice." (PMID 34944428, 2021). "In addition, we found that after GL administration, the plasma levels of IL-6 and TNF-α in the CC + GL group were lower than those in the CC group, suggesting that GL attenuates inflammation in AOM/DSS-induced colitis." (PMID 33807620, 2021). "In the current study, the decrease in inflammatory cytokines by Ala-Gln (not by Gln with IL-1β and TNF-α) indicated that the extent of colitis was ameliorated by Ala-Gln, which has better beneficial effects than Gln." (PMID 34046146, 2021). "Interestingly, a recent study demonstrated that TNFα inhibitors concomitantly with combined anti-PD-1 and anti-CTLA-4 antibodies improved immune related colitis in addition to enhanced anti-tumor efficacy." (PMID 33571254, 2021). "Macroscopic and microscopic colitis in sedentary SD mice was accompanied by a significant decrease in CBF, and a significant increase in the colonic expression of tumor necrosis factor-alpha (TNF-α), IL-6, IL-1β and leptin mRNAs and decrease in the mRNA expression of adiponectin." (PMID 33557311, 2021). "In a chemically induced colitis in mice, an increase of GP2 expression in the pancreas has been observed, which has been an effect of enhanced production of pro-inflammatory cytokines such as TNF." (PMID 34064706, 2021). "When colitis in mice was induced via IL-10−/−, it was shown that the disease worsened in combination with SERT deletion, which was accompanied by increased levels of IL-6 and TNF-α mRNAs." (PMID 34502396, 2021). "The majority of published studies performed using the experimental models of colitis have indicated that the altered immune response was correlated with the increasing release of pro-inflammatory cytokines, including IFN γ, TNFα, IL-6, IL-1β, GM-CSF, and IL-17A." (PMID 34970585, 2021). "Moreover, in mice and piglets, the tryptophan supplementation reduced the symptoms of DSS-induced colitis, improved histology and intestinal permeability, and decreased the levels of local inflammatory mediators, such as IFN-γ and TNF-α." (PMID 34257825, 2021).
colitis (continued). "This study showed that L. plantarum ZS62 could regulate IL-1β, IL-12, TNF-α, IL-10, COX-2, iNOS, NF-κB p65, and IκB-α expression in the colon tissues of mice with enteritis to inhibit colitis." (PMID 34745426, 2021). "Respect to MR-409, MIA-690 showed higher efficacy in inhibiting prostaglandin (PG)E2, 8-iso-PGF2α and serotonin (5-HT) levels, as well as tumor necrosis factor (TNF)-α, interleukin (IL)-6 and nitric oxide synthase gene expression in colon specimens of DSS-induced colitis." (PMID 33510215, 2021). "Indeed, anti-TNF-α agents such as infliximab (anti-TNF-α antibody) are commonly used, after initial corticosteroid therapy, for the management of ICI-related colitis." (PMID 33777008, 2021). "Likewise, black raspberry extract attenuated TNF-α and IL-1β expressions, and NF-κB and COX-2 activity in mice with DSS-induced colitis." (PMID 32722619, 2020). "Alleviating intestinal inflammation in the DSS-induced colitis mouse model; Attenuating leukocyte infiltration in the colon; Reducing mesenteric lymph node enlargement; Decreasing the expression of VCAM-1, E-selectin, and TNF-α in colon blood vessels." (PMID 33553219, 2020). "Likewise, in a mouse model of dextran sulfate sodium (DSS)-induced colitis, upon UC-MSC exosome treatment, macrophage infiltration to the tissue was reduced along with downregulation of IL-1β, IL-6, IL-7, TNFα and iNOS in colon tissue and spleen." (PMID 32595362, 2020). "The IL-10 cytokine family has been shown to facilitate the gut antimicrobial defense and promote mucosal barrier integrity and repair by activating STAT3, while IL-17, TNF-α, and IFN-γ induce colitis by disrupting the mucosal barrier function of the immune system." (PMID 32670220, 2020). "The colon of EV-treated mice showed reduced levels of inflammatory cytokines (TNF-α, IFN-γ, IL-1β, IL-6 and iNOS) and elevated levels of an anti-inflammatory/regulatory cytokine (IL-10), compared to that of untreated mice with colitis and TSG-6-depleted EV-treated mice." (PMID 32040478, 2020). "The antigen invasion can activate the mucosal immune response, resulting in the release of proinflammatory cytokines from macrophages, such as tumor necrosis factor (TNF)-α, interleukin (IL)-1β, IL-6, and IL-8, which can exacerbate inflammatory severity and colitis." (PMID 33664740, 2020). "Similarly, our study showed that SSW suppressed DSS-induced expression of cytokines, such as IL-6, IL-1β, TNF-α, and COX-2, and besides, alleviated DSS-induced colitis symptoms in mice." (PMID 32708415, 2020). "However mucosal TNF transcript in combination with the histological RHI score was able to predict, with high precision, the most severe colitis outcomes needing biological or surgical treatment, within the first year of disease." (PMID 33008302, 2020). "It was observed that the plasma TNF-α level had significantly increased in the colitis group compared to the control group (p <0.01) and the level of TNF-α from the rectal tissue was significantly increased in the colitis group (p <0.000)." (PMID 32555936, 2020). "Previous results have shown that probiotic bacteria could downregulate TNF-α production and upregulate IL-10 in a rat model of trinitrobenzene sulfonic acid (TNBS)-induced colitis." (PMID 32983062, 2020). "As a derivative of coptisine, (±)-8-ADC (75, 150, and 300 mg/kg) treatment activates the transcriptional activity of X-box binding protein 1 and decreases NF-κB expression, subsequently reduces secretion of myeloperoxidase, TNF-α, IL-6 and IL-1β in the colon of DSS-induced colitis mouse." (PMID 32063999, 2020). "Since the increased production of TNF-α and the infiltration of neutrophils have been described as key factors in the inflammatory damage observed in DSS-induced colitis, we evaluated the colon MPO activity as an indirect marker of neutrophil infiltration and the concentration of colon TNF-α." (PMID 33042131, 2020).
colitis (continued). "Moreover, uvaol significantly reduces mRNA expression and production of pro-inflammatory cytokines (TNF-α, IL-6, IL-1β, and MCP-1) and infiltration of macrophages in colonic tissues of colitis mice." (PMID 32411289, 2020). "Western blot analysis of colon tissues revealed that cyclooxygenase-2, tumor necrosis factor alpha (TNF-α), and phosphorylated signal transducer and activator of transcription-3 (p-STAT3) were significantly decreased in the colitis + 5-ASA group, whereas forkhead box P3 (FOXP3) was increased." (PMID 33092149, 2020). "Interestingly, we found that colitis results in the upregulation of IL-1β, IFN-γ, and TNF-α mRNA transcripts and the reduced expression of tight junction proteins." (PMID 32855978, 2020). "Evidences have demonstrated that H. pylori infection decreased the pro-inflammatory cytokines (TNF-α, IFN-γ, IL-1β, IL- 6, IL-17A and IL23) in colitis mouse models, and we also have reported that IL-6 and IL23 expression were down-regulated in H. pylori-infected chronic colitis mice." (PMID 33201893, 2020). "Moreover, studies have showed that cytokines licensed MSCs are more effective to treat some diseases such as EAE and colitis via promoting the immunomodulation of MSCs after IFN-γ and TNF-α treatment." (PMID 32733020, 2020). "In addition, the oral administration of Li. fermentum 5716 alleviated trinitrobenzene sulphonic (TNBS)-induced colitis in rats by increasing the glutathione (GSH) levels and decreasing TNF-α and NO production." (PMID 33266127, 2020). "Trefoil factors (TFF) and anti-tumor necrosis factor-α (TNF-α) nanobodies (single domain antibody fragments) are other therapeutic substances that have been constitutively expressed in L. lactis and tested in DSS-induced colitis in mice." (PMID 32296696, 2020). "In addition to these effects, RES administration suppressed the expressions of MCP-1, cytokine-induced neutrophil chemoattractant 1 (CINC-1), TNF-α, IL-1β, IL-6 and IL-12 in rats with TNBS-induced colitis." (PMID 32722619, 2020). "Together with vitamin D and its proposed anti-inflammatory properties, vitamin D may reduce colitis by regulating COX-2, TNF-α, NF-κB through IkBa expression, RXR signaling, and vitamin D-activating enzymes CYP24A1 and CYP27B1." (PMID 32422882, 2020). "Although previous studies in the DSS-induced colitis mouse model demonstrated anti-inflammatory effects of IMD with reduction of TNF-α and IL-6, we did not see any effect on these cytokines." (PMID 32679670, 2020). "For example, TNFα, a critical driver of IEC shedding in colitis, induces superoxide generation via NOX2, NOX1 and the mitochondria, which will trigger, depending on the context, apoptosis, necroptosis, survival and further upregulation of proinflammatory cytokines such as TNFα and IL-6." (PMID 33059312, 2020). "IL-2 knockout C57BL/6 mice develop a colon inflammation comparable to the human ulcerative colitis, in which the cytokine profile is consistent with a Th1-type host immune response leading to an increase of IFN-γ and TNF-α expression levels." (PMID 32708322, 2020). "In addition, the alteration of pro- and anti-inflammatory cytokine levels, such as IL-6, IL-1β, TNF-α, and IL-10, in the serum of the DSS-induced colitis mice were determined by ELISA." (PMID 33391246, 2020). "Intratracheal OVA-induced colitis resulted in production of T-bet mediated cytokines, including TNF-α, IL-6, and IFN-γ in normal mice, while OVA exposure of T-bet deficient mice failed to result in induction of colitis." (PMID 30949176, 2019). "Accordingly, combined with the results of RNA-seq in mouse colitis, our study showed that CT55 could regulate the production of TNF-α by affecting NF-κB activation in HCT116 cells, which might explain how CT55 functions in CAC." (PMID 30944312, 2019). "In these mice, lack of KNG1 reduced colitis development, infiltration of inflammatory cells into the gut mucosa, and inflammatory cytokine levels (e.g., TNFα, IFN-γ, IL-1β, and IL-6)." (PMID 31623319, 2019).
colitis (continued). "Recent work in mouse models of cancer has shown that co-administration of ICI and anti-TNFα upfront led to improved tumor responses and decreased colitis severity, an approach that has not yet be studied in prospective trials in humans." (PMID 31439050, 2019). "For example, SCFAs enemas did not prevent or reduce intestinal damage in TNBS-induced colitis in rats, while butyrate reduced colonic mucosal damage and serum inflammatory cytokines (IL-6, TNF-α, and IL-1β) in DSS-treated mice." (PMID 30915065, 2019). "Studies on IL-10 knockout mice have shown that concurrent vitamin D receptor (VDR) knockout leads to severe and accelerated IBD, whereas administration of exogenous vitamin D or a VDR agonist in IBD mouse models reduces tumor necrosis factor (TNF)-α and suppresses colitis." (PMID 31352652, 2019). "Levels of pro-inflammatory cytokines IL-6, IL-8, and TNF-α were all increased extremely significantly in colitis group compared with the negative control (CON)." (PMID 31726738, 2019). "It has been previously demonstrated that induction of colitis by 2,4,6-trinitrobenzene sulfonic acid (TNBS) increases cytokine levels (IL-1β and TNF-α) in the hippocampus and that TNF-α is the most important in mediating microglia activation and this was linked to a higher seizure susceptibility." (PMID 31562378, 2019). "Our findings revealed that EEP suppressed protein expression levels of inducible pro-inflammatory enzymes (COX-2 and iNOS) and mRNA expression levels of cytokines (IL-6, IL-1β, and TNF-α) due to inhibitory effects of EEP on phosphorylation of NF-κB and STAT3 in DSS-induced colitis mice." (PMID 30621304, 2019). "In a TNBS rat colitis model, Escherichia coli Nissle 1917, at low doses of the strain (107cfu/day), has been demonstrated to reduce the disease activity index, colonic MPO activity, and TNF‐α levels and to increase IL‐10 expression." (PMID 31572604, 2019). "Considering clinical characteristics, some studies have demonstrated that, in CD patients, young age, isolated colitis, and elevated CRP levels are predictors of response to anti-TNF therapy, while smoking and disease duration more than 2 years are predictors of non-responders." (PMID 31316377, 2019). "In TNBS-colitis, VIP KO mice are resistant to colitis with lower levels of TNF-α and IL-6103." (PMID 31559013, 2019). "Treatment with IMD did not improve typical colitis symptoms, however, IMD treatment was associated with a significant reduction in the expression of pro-inflammatory mediators TNF-α and IL-8, as well as TLR4." (PMID 31731774, 2019). "who reported an experimental colitis-induced rise of hippocampal TNF-α, but not IL-1ß gene expression." (PMID 31882991, 2019). "Although these experiments were conducted in a mouse model of DSS-induced colitis, CGA could similarly inhibit the release of proinflammatory cytokines, such as MPO and TNF-α, in ulcerative colitis." (PMID 30971953, 2019). "Therefore, it can be suggested that in both colitis and NEC models, TNF-α regulates apoptosis in intestinal epithelial cells via the process of autophagy." (PMID 30764829, 2019). "In addition, ALA significantly reduced the expression of pro-inflammatory genes, the activity of MPO, and the production of TNF-α, IL-6, NO and PGE2 in DSS colitis mice." (PMID 31719637, 2019). "TNBS-induced colitis included the secretion of various pro-inflammatory cytokines, such as IL-12, which played an important role in differentiation of T lymphocytes into Th1 effector cells that synthesize interferon gamma (IFN-γ) and TNF-α." (PMID 31546840, 2019). "Furthermore, the use of HDACs inhibitors (e.g., valproic acid) reduce disease severity and inhibit colonic proinflammatory cytokines (TNF-α, IFN-γ, and IL-6) in experimental murine colitis." (PMID 30915065, 2019).